TIPARP-AS1 (TIPARP antisense RNA 1)
Synonyms: LINC00886
Gene: Long non-coding RNA gene on chromosome 3 (156,634,399 to 156,817,062, reverse strand). Ensembl gene ENSG00000243926.
Diseases named in the same sentence as TIPARP-AS1 in open-access papers:
TIPARP-AS1 is named in the same sentence as 5 diseases in open-access papers, as found by Europe PMC text mining. Sharing a sentence is not in itself a finding about the gene and the disease.
TIPARP-AS1 shares sentences with these, for which no sentence is quoted: cancer (3 papers); ovarian carcinoma (2); tumor (2); breast carcinoma (1); laryngeal squamous cell carcinoma (1).